PSMD14 (proteasome 26S subunit, non-ATPase 14)
Diseases named in the same sentence as PSMD14 in open-access papers (continued):
Sharing a sentence is not in itself a finding about the gene and the disease.
osteosarcoma (9 papers, 2022 to 2025). A usually aggressive malignant bone-forming mesenchymal neoplasm, predominantly affecting adolescents and young adults. "High expression of PSMD14 in osteosarcoma patients was associated with a low survival rate and high risk of metastasis and recurrence." (PMID 38863002, 2024). "Overexpression of PSMD14 was associated with osteosarcoma patients’ pathological grade and clinical stage, and PSMD14 was an independent poor prognostic factor." (PMID 38053170, 2023). "The results are in line with a previous study that suggested a correlation between elevated PSMD14 expression and a higher-risk category (younger age group, ≤ 20.83 years of age), metastasis within five years, and a higher tumour grade in osteosarcoma patients." (PMID 38748263, 2024). "PSMD14 is substantially expressed in osteosarcoma and may be an independent risk factor associated with poor prognosis." (PMID 38053170, 2023). "Therefore, the results indicated that PSMD14 overexpression may be substantially associated with osteosarcoma progression." (PMID 38053170, 2023). "PSMD14 expression was obviously elevated in osteosarcoma tissue, and PSMD14 knockdown effectively inhibited the proliferation, migration, and invasion of osteosarcoma cells." (PMID 40066751, 2025). "According to their results they pointed out that PSMD14/Rpn11could be a molecular target of the drug capzimin in osteosarcoma." (PMID 37377390, 2023). "To examine the impact of PSMD14 on the malignant biological behaviors of osteosarcoma cells, we first infected osteosarcoma cells (Saos-2 and U2OS) with lentiviruses expressing shRNA to inhibit PSMD14 expression." (PMID 38053170, 2023). "Considering the osteosarcoma acquired and innate resistance, we evaluated the role of PSMD14 in the progression of osteosarcoma cells resistant to anlotinib." (PMID 38053170, 2023). "Compared to normal osteoblast cells, PSMD14 was elevated at both the mRNA and protein levels in osteosarcoma cells, with Saos-2 and U2OS exhibiting the highest expression levels." (PMID 38053170, 2023). "Consistent with the in vitro data, PSMD14 expression was higher in tumor tissues than in normal osteosarcoma tissues." (PMID 38053170, 2023). "The role of PSMD14 in the malignant phenotype of osteosarcoma and its molecular pathway was explored by a series of studies, including Western blotting, cell amplification assay, transwell assay, and tumor growth." (PMID 38053170, 2023). "Then, we investigated the mRNA and protein expression of PSMD14 in the osteosarcoma tumor tissues (“T”) and normal bone tissues (“N”) of 13 osteosarcoma patients." (PMID 38053170, 2023). "Thirdly, although we have undertaken several functional investigations on the role of PSMD14 in developing anlotinib resistance in osteosarcoma, it has to be determined if this occurs by the PI3K/Akt/m-TOR pathway." (PMID 38053170, 2023). "Using transwell assays, we subsequently investigated the impact of PSMD14 knockdown on osteosarcoma cell motility." (PMID 38053170, 2023). "CCK-8 assays demonstrated that the knockdown of PSMD14 significantly reduced osteosarcoma cell viability to around 50% of control shRNA-treated cells at 96 h." (PMID 38053170, 2023). "Our results imply that PSMD14 knockdown induced osteosarcoma cell apoptosis and inhibited in vitro cell proliferation." (PMID 38053170, 2023). "To further study the significance of PSMD14 in osteosarcoma, we created a stable knockdown of PSMD14 expression in human osteosarcoma cell lines Saos-2 and U2OS using lentivirus-mediated shRNA." (PMID 38053170, 2023). "This study aimed to examine the function and mechanism of PSMD14 in the biological behavior of osteosarcoma and its role in anlotinib resistance." (PMID 38053170, 2023). "To determine the role of PSMD14 in osteosarcoma, we examined the expression of PSMD14 mRNA and protein in four human osteosarcoma cell lines (MG63, Saos-2, 143B, and U2OS) and two normal human osteoblasts (NHOst and hFOB 1.19)." (PMID 38053170, 2023).
osteosarcoma (continued). "To investigate the activities of PSMD14 on osteosarcoma cells, we conducted various in vitro and in vivo investigations." (PMID 38053170, 2023). "Based on the data of transwell assay, the migration abilities of osteosarcoma cells were significantly enhanced following PSMD14 upregulation, and similar results were found in invasion abilities." (PMID 38053170, 2023). "We identified PSMD14 gene as a possible osteosarcoma biomarker, and/or a possible therapeutic target." (PMID 34383385, 2022). "In this study, we utilized existing osteosarcoma gene expression profile datasets from Gene Expression Ominbus (GEO) and identified PSMD14 as a top differential expressed gene (DEG)." (PMID 34383385, 2022). "We further analyzed osteosarcoma patient dataset from TARGET database by comparing PSMD14 high expression patient group to PSMD14 low expression patient group." (PMID 34383385, 2022). "When we compared the PSMD14 gene expression level between the patients with different Huvos Grade of osteosarcoma, we found that higher grade, that is, grade 4 had higher level of PSMD14 expression compare to grade 2 and grade 3." (PMID 34383385, 2022). "Our next goal is to confirm the protein level expression of PSMD14 in human osteosarcoma biopsies, and to further prove the possibility of PSMD14 as a prognosis marker and/or therapeutic target." (PMID 34383385, 2022). "By further analyzing the data, we found that high expression of PSMD14 was significantly correlated to higher osteosarcoma grade and metastasis." (PMID 34383385, 2022). "Taken together, in this study we reported that PSMD14 was significantly up‐regulated in osteosarcoma compare to normal tissue in all datasets we analyzed." (PMID 34383385, 2022). "The high expression level of PSMD14 was found to be correlated with metastasis and worse prognosis in osteosarcoma." (PMID 34383385, 2022). "Higher PSMD14 expression in osteosarcoma had positive correlation with higher infiltration of CD8+ T cells, neutrophils and myeloid dendritic cells." (PMID 34383385, 2022). "Based on the novelty and our preliminary screens results, we did further analysis on the correlation of PSMD14 expression and osteosarcoma clinical features." (PMID 34383385, 2022). "In vitro, PSMD14 overexpression stimulated osteosarcoma cell proliferation." (PMID 38053170, 2023). "This suggests that PSMD14 promotes osteosarcoma resistance to anlotinib in resistant sublines." (PMID 38053170, 2023). "PSMD14 expression was elevated in osteosarcoma tissues compared to normal tissues." (PMID 38053170, 2023). "Recent research suggests that PSMD14 overexpression is related to a poor prognosis and may be a possible therapeutic target for osteosarcoma patients." (PMID 38053170, 2023). "Our findings suggest that PSMD14 may be an oncogenic gene that promotes osteosarcoma tumor growth and resistance to anlotinib by the PI3K/AKT/mTOR pathway." (PMID 38053170, 2023). "Moreover, the expression of PSMD14 was an independent risk factor for worse DFS and overall survival in patients with osteosarcoma." (PMID 38053170, 2023). "The expression level of PSMD14 was found to be highly correlated to osteosarcoma prognosis." (PMID 34383385, 2022). "By using relative larger sample sized GSE42352 dataset, the receiver operating characteristic (ROC) showed that PSMD14 expression could positively predict whether the tissue was osteosarcoma." (PMID 34383385, 2022). "In order to further understand whether high expression of PSMD14 in osteosarcoma is correlated to clinical features, we analyzed the correlation of PSMD14 expression level and osteosarcoma patients' clinical data from dataset GSE42352." (PMID 34383385, 2022). "However, by identifying from the gene expression, it seemed that CD8+ T lymphocytes were relatively abundant in the PSMD14 high expression osteosarcoma tumors." (PMID 34383385, 2022). "Gene set enrichment analysis was further performed for the DEGs related to PSMD14 in osteosarcoma." (PMID 34383385, 2022).
osteosarcoma (continued). "In our work, we discovered that in vivo and in vitro overexpression of PSMD14 was adversely correlated with a poor prognosis in osteosarcoma; PSMD14 may induce malignant osteosarcoma characteristics by the PI3K/AKT/mTOR pathway, according to a preliminary study." (PMID 38053170, 2023). "Studies revealed that PSMD14 may be a viable osteosarcoma treatment target." (PMID 38053170, 2023). "Therefore, PSMD14 may provide a viable method for reversing osteosarcoma’s targeted drug resistance." (PMID 38053170, 2023). "PSMD14 may play an oncogenic function in osteosarcoma cell proliferation, invasion, and migration." (PMID 38053170, 2023). "Therefore, it would worthwhile to further investigate whether PSMD14 plays any roles in osteosarcoma cell processes, and whether PSMD14 can serve as an osteosarcoma therapeutic target." (PMID 34383385, 2022). "For instance, the possibility that PSMD14 high expression tumor cells could induce CD8+ T lymphocytes senescence or exhaustion could be an explanations for the positive correlation between CD8+ T lymphocytes, PSMD14 high expression and worse prognosis in osteosarcoma." (PMID 34383385, 2022). "Moreover, we established anlotinib-resistant osteosarcoma sublines and verified that PSMD14 was significantly expressed in the sublines and that PSMD14 knockdown could reduce the proliferation, migration, and invasion of resistant lines, as well as reverse anlotinib resistance." (PMID 38053170, 2023). "However, PSMD14’s function and mechanism in osteosarcoma remain unknown." (PMID 38053170, 2023). "Furthermore, we developed osteosarcoma cell lines (OE-U2OS and OE-Saos-2) with stable overexpression of PSMD14." (PMID 38053170, 2023). "PSMD14 knockdown substantially reduced the migration and invasion of U2OS and Saos-2 cells, and we also discovered that wound healing was impaired in both osteosarcoma cell lines." (PMID 38053170, 2023). "We utilized GSE42352 dataset to identify genes that were differentially expressed between the high and low PSMD14 expression groups in osteosarcoma, by dividing the GSE42352 cohort into PSMD14 high expression and PSMD14 low expression groups based on the median expression level of PSMD14." (PMID 34383385, 2022). "Osteosarcoma patients with PSMD14 overexpression had a lower disease-free survival and overall survival, as shown by the analysis of osteosarcoma data from the TARGET database using the GEPIA online software, which suggested that increased expression of PSMD14 predicted poor prognosis." (PMID 38053170, 2023). "However, due to the limitation of bioinformatics analysis, the protein level of PSMD14 in osteosarcoma is not well studied." (PMID 34383385, 2022). "Gong considered that a high expression of PSMD14 in tumor cells may lead to aging or failure of CD8+ T cells, which may explain the positive correlation between high expression of CD8+ T cells and PSMD14 and poor prognosis in osteosarcoma." (PMID 35898492, 2022). "But whether PSMD14 plays any roles in osteosarcoma is not studied." (PMID 34383385, 2022). "However, whether PSMD14 plays any roles in osteosarcoma is not elucidated." (PMID 34383385, 2022).
lymph node metastasis (8 papers, 2020 to 2025). "Increased PSMD14 levels were associated with lymph node metastasis, pleural invasion, poor tumor differentiation, and advanced clinical stages." (PMID 40475775, 2025). "High PSMD14 protein expression was associated with lymph node metastasis (N1-3, p = 0.002) and advanced stages (III–IV, p = 0.002)." (PMID 35750900, 2023). "The results revealed that PSMD14 had significant differences in Lymph node metastasis and TNM stage." (PMID 40066751, 2025). "Furthermore, PSMD14 expression was found to correlate with lymph node metastasis and late clinical stage (P = 0.0139 and P = 0.029, respectively)." (PMID 38017133, 2024). "Univariate Cox regression analysis demonstrated that tumor size, lymph node metastasis, TNM stage, and PSMD14 expression were correlated with OS and DFS in LAUD patients." (PMID 32226511, 2020).
esophageal cancer (7 papers, 2021 to 2025). A primary or metastatic malignant neoplasm involving the esophagus. "In esophageal carcinoma, PSMD14 inhibitors can diminish the association between PSMD14 and Snail, promote Snail ubiquitination and degradation, limit EMT, and inhibit ESCC cell metastasis, stemness, and chemotherapy sensitivity." (PMID 38053170, 2023). "Besides, PSMD14 could associate with snail, which inhibits snail poly-ubiquitination and degradation in esophageal cancer." (PMID 38017133, 2024). "The expression of PSMD14 was reported to correlate with poor overall survival in several human malignancies, such as liver cancer and esophageal cancer." (PMID 38017133, 2024). "PSMD14 is highly expressed in esophageal cancer in esophageal cancer, and inhibition of PSMD14 inhibits tumor cell migration, invasion and EMT." (PMID 37853322, 2023). "TCGA database analysis revealed that high concomitant PSMD14/SNAIL expression predicted shorter overall survival in esophageal cancer." (PMID 33897885, 2021). "The analysis of esophageal cancer (EC) dataset in TCGA (The Cancer Genome Atlas) database by using GEPIA online software (gepia.cancer-pku.cn) demonstrated that compared with normal esophageal tissues, PSMD14 was overexpressed in esophageal cancer." (PMID 33897885, 2021). "PSMD14 increases the stability of the Snail protein, a transcription factor associated with epithelial-mesenchymal transition (EMT), thus inducing metastasis in esophageal cancer cells." (PMID 40016178, 2025). "For example, PSMD14 could deubiquitinate snail protein and promote esophageal cancer cell EMT (Epithelial Mesenchymal Transition)." (PMID 38017133, 2024). "Additionally, we analyzed TCGA database and found that high concomitant PSMD14/SNAIL expression indicated worse outcome of patients with esophageal cancer." (PMID 33897885, 2021).
glioma (7 papers, 2020 to 2025). A benign or malignant brain and spinal cord tumor that arises from glial cells (astrocytes, oligodendrocytes, ependymal cells). "Conditions linked to PSMD14 include glioma, multiple myeloma, and breast cancer, underscoring its characterization as an oncogene." (PMID 40475775, 2025). "ECT2 promoted glioma cell proliferation by regulating the expression of the deubiquitinating enzyme PSMD14 to affect the degradation of the TF E2F1." (PMID 38467631, 2024). "In this study, our objective was to analyse whether SMB6, PSMD9, UBB, PSMD12, PSMB10, PSMA5, and PSMD14 are independent prognostic factors for glioma." (PMID 34868920, 2021). "The ECT2/PSMD14/PTTG1 axis promoted glioma proliferation by stabilizing E2F1." (PMID 33381564, 2020). "Furthermore, we corroborated PSMD14 expression in clinical specimens from LUAD, LIHC, HNSC, and glioma, substantiating its upregulation during the initiation and progression of various tumors." (PMID 40475775, 2025).
liver cancer (7 papers, 2015 to 2025). An epithelial or non-epithelial malignant neoplasm that arises from the liver. "For example, PSMD14 could deubiquitinase and stabilize TGF-beta, which facilitates liver cancer progression." (PMID 38017133, 2024).
lung carcinoma (6 papers, 2020 to 2025). "We collected clinical data from a cohort of 77 patients to assess the prognostic relevance of the PSMD14 protein, along with its association with clinical and pathological characteristics in lung cancer." (PMID 40475775, 2025). "In the domain of lung cancer research, the expression level of PSMD14 has been identified as having a strong relationship with patient prognosis." (PMID 40475775, 2025). "In conclusion, the involvement of PSMD14 in the progression of lung cancer necessitates further investigation." (PMID 40475775, 2025). "To assess the influence of varying levels of PSMD14 expression on the progression of lung cancer, we employed GSEA to pinpoint the biological functions and pathways that were most significantly enriched." (PMID 40475775, 2025). "Psmd14, one of our main depletion hits, stabilizes human epidermal growth factor receptor 2 (HER2) and is upregulated in lung carcinoma associated with poor prognosis." (PMID 36313646, 2022). "Notably, a parallel mechanism was reported in lung cancer, where PSMD14 promotes metastasis by deubiquitinating Smad3 to augment TGF-β1/Smad3 signaling and is associated with poor patient prognosis." (PMID 41488674, 2025). "Although the role of PSMD14 has been reported in several cancer types 17, 19, 21, 22, 25, 34, its involvement in lung cancer has not been elucidated." (PMID 32226511, 2020).
colorectal cancer (5 papers, 2021 to 2023). A primary or metastatic malignant neoplasm that affects the colon or rectum. "PSMD14 can also mediate deubiquitination and enhance the stability of ALK2, an oncogenic serine/threonine kinase, thereby promoting tumor growth and chemoresistance in colorectal cancer." (PMID 34382324, 2021).
pancreatic ductal adenocarcinoma (5 papers, 2023 to 2025). An infiltrating adenocarcinoma that arises from the epithelial cells of the pancreas. "Association between PSMD14 expression and clinicopathological characteristics of pancreatic ductal adenocarcinoma (PDAC) patients." (PMID 40066751, 2025). "In another study, the expression of PSMD6, PSMD9, PSMD11, and PSMD14 was significantly associated with a decreased chance of survival in patients with pancreatic ductal adenocarcinoma." (PMID 37349676, 2023). "This study further clarified the role of PSMD11 and PSMD14 in the occurrence and development of pancreatic ductal adenocarcinoma." (PMID 40182048, 2025). "In this study, bioinformatics analysis revealed the expression of PSMD11 and PSMD14 in pancreatic ductal adenocarcinoma, which can be used as biomarkers for the prognosis of patients with PDAC." (PMID 40182048, 2025). "In pancreatic ductal adenocarcinoma patients, high levels of PSMD6, PSMD9, PSMD11, and PSMD14 are associated with a lower rate of survival." (PMID 36934426, 2023). "PSMD11 and PSMD14 are highly expressed in pancreatic ductal adenocarcinoma tissues and are correlated with the degree of malignancy of pancreatic ductal adenocarcinoma; thus, PSMD11 and PSMD14 can be used as potential prognostic biomarkers and therapeutic targets for PDAC patients." (PMID 40182048, 2025). "Bioinformatics analysis revealed that the expression levels of PSMD11 and PSMD14 mRNAs were significantly higher in pancreatic ductal adenocarcinoma (PDAC) tissues than in normal pancreatic tissues and that this high expression was correlated with a poor prognosis in patients with PDAC." (PMID 40182048, 2025). "Analysis of the patients’ clinical data revealed that the expression of both PSMD11 and PSMD14 was significantly correlated with lymph node metastasis, TNM grade, degree of differentiation, and poor prognosis in pancreatic ductal adenocarcinoma patients." (PMID 40182048, 2025). "Based on the information collected for our pancreatic ductal adenocarcinoma patients and immunohistochemical staining on their pathological sections, we showed that PSMD11 and PSMD14 were mainly expressed in the cytoplasm." (PMID 40182048, 2025).